MYD88 (MYD88 innate immune signal transduction adaptor)
Diseases named in the same sentence as MYD88 in open-access papers (continued):
Sharing a sentence is not in itself a finding about the gene and the disease.
lymphoma (continued). "B-cell receptor (BCR) signaling has been observed in lymphomas driven by mutated MYD88, even without activating the BCR pathway mutations." (PMID 32005797, 2020). "Furthermore, somatically acquired MYD88 mutations, a component of the Toll-like receptor danger pathway, have been implicated in cell survival control through the BCR in this lymphoma subtype." (PMID 33050534, 2020). "Together, these data suggest that mutant forms of MYD88 drive development of lymphoma." (PMID 30301877, 2018). "In human lymphoma cell lines and primary lymphoma cells, cerdulatinib demonstrates broad anti-tumor activity in diffuse large B-cell lymphoma including GCB and ABC tumor cells with ibrutinib-resistant MYD88 or CARD11 mutations." (PMID 28088788, 2017). "Indeed, inhibition of the MyD88 downstream kinases IRAK1/4 with small molecule inhibitors was shown to effectively block TLR signaling cascade in vitro and to induce cell death of lymphoma cells bearing specific MyD88 mutations." (PMID 22973499, 2012). "Therefore, detection of MyD88 expression may be useful for predicting the prognosis of patients with various cancers, such as lymphoma, ovarian cancer, liver cancer, and colorectal cancer." (PMID 38785969, 2024). "In addition, Myd88 protein expression was increased tumor tissues of lymphoma tissues." (PMID 37953776, 2023). "These lymphomas arise from previously considered immune sanctuary sites and have inferior responses to treatment, are mostly of the non-GCB subtype of DLBCL, and have a high prevalence of combined MYD88/CD79B mutations in >70% of cases, resulting in constitutive NF-κΒ pathway activation." (PMID 33178841, 2020). "We here describe the impact that MYD88 and CD79B activating mutations, two of the most frequent mutations in several DLBCL subtypes, may achieve in the next future in the diagnosis and therapeutics of such a relevant lymphoma subtype." (PMID 33050534, 2020). "Interestingly, VR09 cell line showed unmutated Myd88 gene, differently from what described in recents reports, thus suggesting that lymphomas with plasmacytic features may have different gene patterns." (PMID 23285191, 2012). "Doctors suggested improving the pathological examination of enlarged lymph nodes, bone marrow examination, flow cytometry (lymphoma), FISH (MM + IGH), MYD88, and CXCR4 fusion gene detection." (PMID 39705448, 2024). "As a lymphoma model, we chose the ABC DLBCL cell line U2932 endogenously expressing low levels of wt MyD88." (PMID 36982699, 2023). "MYD88-L265P strongly promotes NF-κB pathway activation, JAK-STAT signaling and lymphoma cell survival." (PMID 37591861, 2023). "A recent study showed that SPOP triggered mixed-linkage ubiquitination of MyD88 in human lymphoma cells and mouse HSCs, suggesting that the SPOP-MyD88 pathway plays a critical role in hematopoietic neoplasms." (PMID 35874839, 2022). "Most of the specimens with a CD79B mutation carried a concomitant MYD88 mutation and were classified as non-GCB lymphomas, which is in concordance to previous studies." (PMID 41295250, 2025). "In univariable survival analyses, neither non-GCB origin, double-expressor lymphoma, LymphGen MCD subtype, or MYD88 pathogenic variants were significantly associated with 5-year survival rates in our cohort." (PMID 38542066, 2024). "More importantly, it can also inhibit the growth of lymphoma and leukemia cells, overcoming the limitations of the BTK inhibitor, ibrutinib, in the treatment of non-mutant MyD88 lymphoma and providing new treatment ideas for WT MyD88 lymphoma." (PMID 38785969, 2024). "Flow cytometry (lymphoma), FISH (MM + IGH) and MYD88 were detected." (PMID 39705448, 2024). "Mutations in CD79B reported to occur in 23% of IgM gammopathy–positive DLBCL, were found in 20% of lymphomas with IgM gammopathy and in 13% of lymphomas without IgM gammopathy, with 13% and 7% of the lymphomas harboring both a CD79B and a MYD88 mutation." (PMID 37566280, 2023).
lymphoma (continued). "In cases of relapsed CNSL, primary lymphoma locations such as testes, breast, and uterine DLBCL have a high prevalence of the non-germinal center B-cell (non-GCB) phenotype and the MYD88/CD79B-mutated genotype with a more reserved prognosis." (PMID 37240953, 2023). "Second, the SPOP-mediated K48-linked ubiquitination and degradation of MyD88 were dominant in Aifantis’s cell system, and triggered nondegradative mixed-linkage ubiquitination of MyD88 was dominant in the human lymphoma cell lines used in Wang’s study." (PMID 32235916, 2021). "Patients with lymphoma involvement in the GI tract had significantly decreased PIM1 (9.1 vs. 25.0%, P = 0.034) and MYD88 (0 vs. 20.8%, P = 0.001) mutations than those without GI tract involvement." (PMID 34557402, 2021). "Pathogenic variants were obvious in some of the most commonly affected genes in lymphomas, such as BCL2, MYD88, NOTCH2, EZH2, and CD79B, and most of them could be identified in matched LB-originated cfRNA." (PMID 34204385, 2021). "Knockdown of MYD88 or use of a MYD88 signaling inhibitor abrogated SYK activation, while expression of mutated but not wild-type MYD88 amplified p-SYK in MYD88-mutated and wild-type lymphoma cells." (PMID 32005797, 2020). "We also observed that HJ901 (10 or 25 mg/kg) treatment suppressed lymphoma growth in a mouse DLBCL xenogeneic tumor model with TMD8 cells harboring the MyD88 L265P mutation, rather than U2932 cells with wild-type MyD88." (PMID 32391356, 2020). "The most frequently mutated genes (PIM1, MYD88, CD79B, and CARD11) are more prevalent in non-GCB DLBCL as has been addressed in previous publications in both extra-nodal and nodal lymphomas." (PMID 29262531, 2017). "More recently, genetic lesions of MYD88 have recently been found to play an important role in lymphoid neoplasms, including ABC- diffuse large B cell lymphomas, central nervous system lymphomas, Waldenstrom macroglobulinemia, and also in T lymphomas." (PMID 23976989, 2013). "For CD79B, irrespective of MYD88 mutational status, mutations were found in 4/28 (14%) of ENT lymphomas, 2/26 (8%) of CNS lymphomas, 2/7 (28%) of lymphoma of the testis, 1/8 (12%) of bone lymphomas, 1/2 (50%) of lymphomas located in the spleen, and 1/16 (6%) of skin lymphomas." (PMID 36051079, 2022). "Another previous study demonstrated the formation of a multiprotein supercomplex composed of MYD88, TLR9, and the BCR (My-T-BCR) as a mode of oncogenic BCR signaling in various lymphomas, yet this was not evident in CLL LN biopsies." (PMID 37100883, 2023). "We also identified the same expression pattern in a mouse lymphoma model of mutant MyD88 (dataset GSE141453) and other available lymphoma datasets (not shown; e.g., GSE50721, GSE56315, and GSE31312)." (PMID 36982699, 2023). "Nevertheless, in our hands wild type MYD88 LPL cases are exceptional (only two documented cases in our archive) and none of them progressed into a more aggressive lymphoma." (PMID 33180881, 2020).
Obesity (79 papers, 2009 to 2025). Accumulation of substantial excess body fat. "Myofibroblast MyD88-deficient (SMAMyD88−/−) mice were protected from diet-induced obesity and developed fewer and smaller liver tumors." (PMID 38291436, 2024). "Lastly, a 19-year-old-patient with MyD88 deficiency (OMIM 602170) with obesity (P24) required conventional nasal prongs for 3 days, and his sister, 16 years old and affected by the same IEI (P25), had non-hypoxemic pneumonia." (PMID 36742319, 2023). "We previously showed that the elevated adipose gene expression of TLR4, TLR2, and MyD88 in people with obesity/T2D was associated with the IRAK1 gene expression." (PMID 36552771, 2022). "Although several TLRs and down-stream signaling molecules including MyD88, and NLRPs have been implicated in the development of obesity, these proteins are broadly expressed on intestinal DCs, macrophages, and T cells." (PMID 35812447, 2022). "Regression analysis stratified by obesity status revealed the independent association of adipose SRA1 expression with MyD88 in NW (N = 12), and with TLR9 in overweight (N = 32) participants." (PMID 36552771, 2022). "TLR4 and MyD88 both play prominent roles in supporting low-grade inflammation in obesity, and deficiency in either protein attenuates obesity and metabolic alterations caused by a HFD." (PMID 33603741, 2020). "Although several cell types can signal through MyD88, their individual contribution to obesity-associated inflammation and metabolic deregulation is still unclear." (PMID 28614714, 2017). "Specific tamoxifen-induced MyD88 deletion in intestinal epithelial cells protects against diet-induced obesity, is associated with increased energy expenditure, improves glucose homeostasis, and reduces hepatic steatosis and whole-body fat mass by 30 %." (PMID 27105827, 2016). "As saturated fatty acids-induced activation of TLR4 is involved in enhancing metabolic disease, MyD88-deficient mice would be expected to attenuate obesity-associated diabetes." (PMID 20824098, 2010). "Moreover, obesity is a well-known metabolic syndrome driven by low-grade inflammation and loss of MyD88." (PMID 40095546, 2025). "Previous studies have shown that MyD88 plays a key role in in obesity-associated NAFLD." (PMID 38291436, 2024). "Moreover, the use of knock-out mice or loss of function mutations in either TLR2, TLR4 or MyD88 also confirmed their role in obesity-associated inflammation." (PMID 34083551, 2021). "5-HT3RAs such as tropisetron can reduce hepatic lesions of obesity-associated fatty liver disease in mice by reducing portal vein plasma endotoxin levels, attenuating the increased MyD88 and tumor necrosis factor-α mRNA expression in the liver, and increasing tight junction proteins in the duodenum." (PMID 33967787, 2021). "In humans, expression of MyD88 has been associated with obesity and metabolic syndrome." (PMID 30417001, 2018). "The underlying mechanism by which MyD88 regulates the development of obesity, metainflammation, and insulin resistance (IR) remains unknown." (PMID 28614714, 2017). "Here, we observed that full deletion of MyD88 is sufficient to cause obesity and IR in mice." (PMID 28614714, 2017). "Besides involving in the classical TLR4-MyD88-dependent signaling pathway related to atheroscleorsis, MyD88 has been also played an important role in obesity-associated inflammatory diseases, including insulin resistance and atherosclerosis." (PMID 26959040, 2016). "This suggests that altered intestinal flora, associated with obesity, may activate downstream inflammatory pathways through MyD88 leading to increased systemic TLR2 and 4 levels and a pro-inflammatory environment." (PMID 27992443, 2016). "IRAK-1 is a critical adapter protein of the TLR/IL-1R/MyD88 signaling pathway and obesity-associated changes in its expression remain unclear." (PMID 26312071, 2015).
Obesity (continued). "Our data suggest that intestinal epithelial MyD88 is a sensor changing host metabolism according to the diet and influences the composition of the gut microbiota thereby influencing energy metabolism and the development of obesity and associated diseases." (PMID 25476696, 2014). "Furthermore, we identified the key bioactive compounds in ECT (Sachaliside, Naringenin, Liquiritigenin, maclurin, and Rhapontigenin) and elucidated its underlying LPS‐TLR4/MyD88/NF‐κB signaling pathway in mitigating obesity‐induced oxidative stress and inflammatory responses." (PMID 40772014, 2025). "However, it is unclear whether TLR and MyD88 signaling in astrocytes is triggered by over-nutrition and thus directly linked to the development of obesity in association with hypothalamic gliosis and inflammation." (PMID 32560726, 2020). "This is further supported by recent evidence demonstrating that astrocytic deletion of IL‐1 (NLRP3‐dependent cytokine) receptor signaling adaptor MyD88 (myeloid differentiation primary response protein) inhibits obesity pathogenesis in mice." (PMID 40304241, 2025). "The increased expression of the MyD88 marker is likely a reflection of obesity, particularly in the context of metabolic syndrome." (PMID 40862415, 2025). "Myd88 serves as an essential adaptor protein for all TLRs, and its deletion in the gut provides partial protection against diet-induced obesity, diabetes, and inflammation." (PMID 38539827, 2024). "In contrast, MyD88 depletion in myeloid cells and intestinal epithelial cells reduced diet-induced obesity, systemic inflammation, and insulin resistance." (PMID 38291436, 2024). "In contrast, deleting MyD88 in intestinal epithelial cells or myeloid cells protects mice from obesity and IR." (PMID 38291436, 2024). "Myeloid differentiation primary response gene 88 (MyD88) can be activated during inflammatory reactions, which often occur in obesity, and results in IR by the activation of IKKβ- nuclear factor κB (NFκB) pathway." (PMID 39201799, 2024). "Blocking CCL9 inhibited Hepa1-6 tumor growth, further demonstrating that CCL9 is a key downstream molecule of MyD88 in myofibroblasts in obesity-related liver cancer." (PMID 38291436, 2024). "Myeloid differentiation ­primary-response gene 88 (MyD88) is the key adaptor for most TLRs, IL-1 receptor (IL-1R), and IL-18 receptor, which have been shown to play a role in obesity and diabetes." (PMID 39872860, 2023). "MyD88 deficiency in the mouse CNS (MyD88ΔCNS) or astrocyte-specific MyD88 knockout protects mice from chronic HFD-induced obesity, and mice exhibit ameliorated hypothalamic reactive gliosis and inflammation." (PMID 36188456, 2022). "Experiments done in mice have found that the hepatocyte deletion of MyD88, a crucial gene in obesity and diabetes, induces changes of specific gut microbes." (PMID 35047580, 2021). "HFD consumption increases the expression of Myd88, an adaptor molecular of TLR signaling, in hypothalamic astrocytes; astrocyte-specific deletion of Myd88 ameliorates hypothalamic reactive gliosis and inflammation and prevents obesity in HFD fed mice." (PMID 34720877, 2021). "Collectively, these observations demonstrate that selective ablation of the Myd88 gene in astrocytes ameliorates diet-induced obesity (DIO) and impaired glucose metabolism by affecting food intake and energy expenditure." (PMID 32560726, 2020). "To analyze the role of astrocyte MyD88 in obesity pathogenesis, we used astrocyte-specific Myd88 knockout (KO) mice fed a high-fat diet (HFD) for 16 weeks or injected with saturated free fatty acids." (PMID 32560726, 2020). "Targeting MyD88 (inducible knock out) after onset of obesity reduced fat mass and inflammation, suggesting a link between microbiota and MyD88 in the development of obesity." (PMID 33178196, 2020).
Obesity (continued). "The present study reports that MyD88 signaling in astrocytes is a key mediator of obesity pathogenesis and highlights its contribution to over-nutrition-induced reactive gliosis and leptin resistance in the hypothalamus." (PMID 32560726, 2020). "In contrast, inducible deletion of Myd88 in intestinal epithelial cells partially protected against diet-induced obesity, diabetes and inflammation." (PMID 33178196, 2020). "The current observations demonstrate that MyD88 signaling in astrocytes is a critical contributor to the hypothalamic inflammation–induced pathogenesis of obesity." (PMID 32560726, 2020). "Our former work demonstrated that TLR4/MyD88/CaMKII signaling pathway contributed to obesity-induced ventricular electrical remodeling." (PMID 32733242, 2020). "Increased MyD88 signalling in the hypothalamus has been found to contribute to fatty acid induced leptin resistance and diet induced obesity." (PMID 29190946, 2017). "Although MyD88 has been studied in the context of obesity, there are still some unsolved questions to be accessed." (PMID 28614714, 2017). "For instance, we found that Deltaproteobacteria was increased in both the obese WT and MyD88 KO mice, which is also consistently increased in obesity induced by HFD in our and previous studies." (PMID 28614714, 2017). "A recent study examined the possibility that MyD88, a central adaptor molecule for the majority of TLRs, acts as a sensor in the interaction between gut microbes and the host in obesity." (PMID 27105827, 2016). "The emerging role of TLR2/4 as immuno-metabolic receptors points to key involvement of TLR/IL-1R/MyD88 pathway in obesity/type-2 diabetes (T2D)." (PMID 26312071, 2015). "Here we discovered that intestinal innate immune system and more specifically intestinal epithelial MyD88 is a primary sensor involved in the cross-talks between nutrients, gut microbes and host during diet-induced obesity." (PMID 25476696, 2014). "These unique features render intestinal epithelial MyD88, an attractive target for preventing or treating diet-induced obesity and metabolic disorders." (PMID 25476696, 2014). "Here we examined the possibility that MyD88 in the intestinal epithelial cell acts as a sensor involved in the interaction between nutrients, gut microbes and the host in obesity." (PMID 25476696, 2014). "Here we report that inducible intestinal epithelial cell-specific deletion of MyD88 partially protects against diet-induced obesity, diabetes and inflammation." (PMID 25476696, 2014). "Here we provide a novel pathway for diet-induced obesity, type 2 diabetes and metabolic disorders and pointed out the major role played by MyD88 in the intestinal epithelial cells on gut microbiota modulation and host energy metabolism." (PMID 25476696, 2014). "To evaluate molecular mechanisms linking obesity-associated diabetes down-stream of TLR4, we investigated physiological role of MyD88 in high-fat diet (HFD)-induced obesity." (PMID 20824098, 2010). "Additionally, it can modulate the gut microbiota, suppress the TLR4/Myd88/NF-κB inflammatory pathway, and effectively combat obesity and hyperlipidemia in mice fed a high-fat diet." (PMID 41584839, 2025). "Animal experiments confirmed its significant weight‐loss and lipid‐lowering effects, primarily by mitigating hepatic oxidative stress and systemic inflammation via the LPS‐TLR4/MyD88/NF‐κB pathway, supporting its potential as a functional food for obesity management." (PMID 40772014, 2025).